CTLA4 (cytotoxic T-lymphocyte associated protein 4)
Diseases named in the same sentence as CTLA4 in open-access papers (continued):
Sharing a sentence is not in itself a finding about the gene and the disease.
nasal polyp (2 papers, 2013 to 2023). "Compared with peripheral blood mononuclear cells (PBMC), the expression of CTLA-4+ Treg cells in local lymphocytes of nasal polyps was significantly increased." (PMID 37176151, 2023). "Single-cell analysis of nasal polyps from patients with CRSwNP found that inhibitory receptors, including LAG3 and CTLA4, were significantly overexpressed in the TH2 TCN1 cells." (PMID 37176151, 2023).
Neonatal sepsis (2 papers, 2024 to 2025). Systemic inflammatory response to infection in newborn babies. "It further confirms the independent association of decreased Treg cell frequency, activation, and homing with EOS, suggesting that Treg, Integrin α4β1, activation markers CTLA-4, PD-1 and CD39 may become robust early markers of neonatal sepsis." (PMID 39072327, 2024).
nephrotic syndrome (2 papers, 2022 to 2023). A collection of symptoms that include severe edema, proteinuria, and hypoalbuminemia; it is indicative of renal dysfunction. "For the first time, CTLA4 rs4553808 gene polymorphism was found to affect the clearance of TAC in the nephrotic syndrome population." (PMID 36457704, 2022). "Therefore, the effect of CTLA4 on TAC in the nephrotic syndrome population deserves to be explored in depth." (PMID 36457704, 2022). "In addition to this, there are also relevant studies suggesting that the pathogenesis of nephrotic syndrome may be related to CTLA4-mediated T-cell dysfunction." (PMID 36457704, 2022).
ophthalmoplegia (2 papers, 2021 to 2022). Weakness or paralysis of at least one of the muscles controlling the movement of the eye. "It is also unknown how combination treatment affects NOirAE incidence and severity, although combined anti-CTLA-4 and anti-PD-1 have been associated with a higher frequency of ophthalmoplegia relative to other adverse events." (PMID 38983573, 2022).
parathyroid adenomas (2 papers, 2022 to 2025). "Even though the expression of PD-1/PD-L1 or CTLA-4 is unknown in normal parathyroid tissue, PD-L1 expression was demonstrated by immunohistochemistry in 8 (30.8%) of 26 parathyroid carcinomas and in 18 (48.6%) of 37 parathyroid adenomas." (PMID 40356787, 2025).
peanut allergy (2 papers, 2020 to 2021). "The study conducted by other researchers also reported similar results, showing that CD86 is an important factor in the induction of peanut allergy and the interaction between CD80 expression on DCs and CTLA-4 expression on T cells are both crucial for the induction of tolerance." (PMID 34177885, 2021).
pemphigus foliaceus (2 papers, 2010 to 2015). Pemphigus foliaceous is a rare superficial pemphigus disease characterized by multiple, pruritic, scaly, crusted cutaneous erosions, with flaky circumscribed patches, localized mostly on the face, scalp, trunk and extremities, often presenting an erythematous base. "CTLA4-ATMSCs or naive ATMSCs transplantation may be beneficial as adjunctive therapy to initiate and maintain the remission of skin lesions caused by pemphigus foliaceus in veterinary medicine." (PMID 25889154, 2015). "This case report describes the successful management of steroid refractory pemphigus foliaceus with CTLA4-ATMSCs and/or naive ATMSCs." (PMID 25889154, 2015). "The objective of this case report is to present the successful management of steroid refractory pemphigus foliaceus with cytotoxic T-lymphocyte antigen 4 (CTLA4)-overexpressing adipose tissue mesenchymal stem cells (ATMSCs)." (PMID 25889154, 2015). "This case report describes the clinical application of CTLA4-ATMSCs and/or naive ATMSCs in steroid refractory pemphigus foliaceus." (PMID 25889154, 2015). "We do not exclude the involvement of the CTLA-4 molecule in PF pathogenesis, but show that CT60 genotypes have no significant impact on pemphigus foliaceus disease susceptibility." (PMID 21637411, 2010).
peritoneal mesothelioma (2 papers, 2018 to 2020). A benign or malignant mesothelial neoplasm that arises from the peritoneum. "The administration of a PDT-based DC vaccine to mice bearing peritoneal mesothelioma led to highly significant survival when compared with sham or control animals treated with anti-CTLA4 antibodies." (PMID 32120810, 2020). "The current immune-based therapies for peritoneal mesothelioma include the treatment with the anti-CTLA4 antibody tremelimumab, and a phase III, randomised trial is ongoing (Clinical Trial NCT01843374)." (PMID 30510965, 2018).
plasmacytoma (2 papers, 2014 to 2016). Plasmacytoma is a localized mass of neoplastic monoclonal plasma cells that represents approximately 5% of all plasma cell neoplasms. "Expression of markers for Treg (FOXP3, CTLA4) and Th17 cells (RORγt) was determined by quantitative real-time PCR in BM aspirates of 46 MM patients, four patients with monoclonal gammopathy of undetermined significance, five solitary plasmacytomas, and five healthy BM donors." (PMID 25099367, 2014).
preeclampsia (2 papers, 2019 to 2025). Preeclampsia is a hypertensive disorder of pregnancy that is characterized by new-onset hypertension with proteinuria presenting after 20 weeks of gestation, and depending on mild or severe forms may initially present with severe headache, visual disturbances, and hyperreflexia. "Although preeclampsia is characterized by a diminished Treg frequency, a well-known alteration, little information is available about the possible role of CTLA-4 in the pathogenesis of the disease." (PMID 31057559, 2019). "Therefore, it is difficult to determine the significance of the CTLA-4 pathway in preeclampsia." (PMID 31057559, 2019). "CD80 and CD86 ligand expression levels on monocytes decrease in preeclampsia, while data about CTLA-4 expression of Treg are not conclusive, increased and unchanged expression patterns were reported as well." (PMID 31057559, 2019).
Respiratory tract infection (2 papers, 2020 to 2021). An infection of the upper or lower respiratory tract. "Most CTLA4+/- patients present with recurrent respiratory tract infections, which is thought to result from deficiency of B cells and immunoglobulin." (PMID 35154081, 2021). "Many CTLA4+/- patients also suffer from recurrent respiratory tract infections but has been reported infrequently as a complication of anti-CTLA4 treatment." (PMID 35154081, 2021). "In addition to lymphocytic pneumonitis, many CTLA4+/- patients have recurrent respiratory tract infections, including pneumonia, sinusitis and otitis media." (PMID 35154081, 2021).
Salmonella Infections (2 papers, 2010 to 2025). Infections with bacteria of the genus SALMONELLA. "Thus, reduction in Treg suppressive potency during the progression of persistent Salmonella infection directly parallels reduced CTLA-4 and increased GITR expression that each independently correlates with this shift in suppression." (PMID 20714351, 2010). "For example, while CTLA-4 expression on Tregs mediates immunosuppression, high levels of CTLA-4 significantly impair the clearance of Salmonella infections in mice." (PMID 40806563, 2025).
septic arthritis (2 papers, 2017 to 2021). "Pre-treatment with CTLA4 Ig (abatacept) significantly increases the susceptibility of mice to S. aureus septic arthritis." (PMID 28264025, 2017). "Septic arthritis mice pretreated with CTLA4-Ig exhibited more severe joint inflammation but lower levels of IL-4 compared to the control mice." (PMID 33546401, 2021). "In contrast, CTLA4-Ig treatment and IL-1 inhibitor aggravated septic arthritis but with no impact on bacteria clearance." (PMID 33546401, 2021).
skin toxicity (2 papers, 2022). "In cohort 2, consisting of patients with biopsy-confirmed irColitis, PD-1 blockade in addition to CTLA-4 blockade increased the risk of additional skin toxicity." (PMID 35740660, 2022).
T-cell leukemia (2 papers, 2016 to 2021). A malignant disease of the T-lymphocytes in the bone marrow, thymus, and/or blood. "In acute B and T cell leukemias, the CTLA-4 expression was mainly cytoplasmic, while in chronic B cell leukemias, it was expressed on both the cell surface and in the cytoplasm." (PMID 26918337, 2016).
uterine tumors (2 papers, 2022 to 2023). "We assessed PD-L1, PD-1, CTLA-4, and IDO expression on paraffin embedded tissue blocks of the uterine tumors using the respective antibodies." (PMID 36104728, 2022).
Vulvar Cancer (2 papers, 2022 to 2025). "TDLN-targeting interventions combining CTLA-4 (in earlier stages) and PD-1 blockade (in later stages) should be considered for vulvar cancer patients, in order to reinvigorate memory T cells and prevent metastatic spread and growth." (PMID 35207374, 2022).
abnormal glucose tolerance (1 paper, 2021). An abnormal resistance to glucose, i.e., a reduction in the ability to maintain glucose levels in the blood stream within normal limits following oral or intravenous administration of glucose. "Also, the TrialNet CTLA4-Ig (abatacept) ongoing trial designed to test whether intervention with Abatacept could prevent or delay the development of abnormal glucose tolerance (AGT) in at-risk relatives of T1D patients." (PMID 33794915, 2021).
Acute tubulointerstitial nephritis (1 paper, 2018). Acute inflammation of the kidney affecting the interstitium of the kidneys surrounding the tubules. "Acute tubulointerstitial nephritis (ATIN) has been increasingly recognized as an important manifestation of kidney injury associated with the use of immune checkpoint inhibitors (anti-PD-1 and anti-CTLA-4)." (PMID 29486725, 2018).
adenoid cystic carcinoma (1 paper, 2024). A malignant tumor arising from the epithelial cells. "The absence of PD-L1 and CTLA-4 and the enrichment of HLA-G in adenoid cystic carcinomas of salivary glands suggested that existing agents targeting PD-L1 or CTLA-4 might be ineffective due to the lack of targets." (PMID 38310272, 2024).
alcoholic cirrhosis (1 paper, 2012). "The CTLA4 polymorphic G allele may confer susceptibility to ALD and, in the homozygous state, to alcoholic cirrhosis." (PMID 23300559, 2012). "The CTLA4 polymorphic G allele may confer susceptibility to ALD and, in the homozygous state, to alcoholic cirrhosis by interfering with the immune response." (PMID 23300559, 2012).
Ascites (1 paper, 2024). Accumulation of fluid in the peritoneal cavity (between the layers of the peritoneum that lines the abdomen). "Previous studies have reported that ascites in OvCa are immunosuppressive and consist of abundant amounts of CTLA-4 as a part of the suppressive mechanism." (PMID 38910324, 2024).
atopic asthma (1 paper, 2018). An asthma that is characterized by symptoms that are triggered by an allergic reaction caused by inhaled allergens such as dust mite allergen, pet dander, pollen and mold. "We thus concluded that adult atopic asthma patients have an increase of circulating CD4+ T cells that are CD25+, FoxP3+, and CTLA-4+, FoxP3+CD25high, or FoxP3+CTLA-4+." (PMID 29507584, 2018). "CCR4+CCR7+ memory, but not CCR4+CCR7− memory, α4+, and CTLA4+ CD4+ T cells in patients show significant clinical implications in atopic asthma." (PMID 29507584, 2018). "Although atopic asthma patients have an increase of Tregs, these cells may not be fully functional, although CTLA-4 could contribute to their suppressive function." (PMID 29507584, 2018).
autoimmune gastritis (1 paper, 2021). Inflammation of the body fundic mucosa of the stomach. "We describe a boy with early-onset severe, refractory autoimmune gastritis and biallelic mutations in the LRBA gene causing a premature STOP-codon who was successfully treated with CTLA4-Ig, abatacept, with long term clinical and endoscopic remission." (PMID 33717114, 2021).
autoinflammatory syndrome (1 paper, 2013). A group of disorders of the innate immune system characterized by attacks of seemingly unprovoked inflammation without significant levels of either autoantibodies or autoreactive T cells more characteristic of autoimmune disease. "Also, the expression of key surface molecules by TR2-deficient Treg cells—namely CTLA-4, GITR (Tnfrsf18), and ICOS —remained unchanged in contrast to our observations in the bone marrow chimera model presenting with a lethal autoinflammatory syndrome." (PMID 24115907, 2013).
Azoospermia (1 paper, 2023). Absence of any measurable level of sperm,whereby spermatozoa cannot be observed even after centrifugation of the semen pellet. "A case report describes a normozoospermic man who developed azoospermia 2 years after treatment with anti-PD1 and anti-CTLA4." (PMID 37240854, 2023).
B cell high grade lymphoma (1 paper, 2018). "It was thought that expression of CTLA-4 on T cells might be associated with a worse prognosis and might represent a prognostic factor for canine B cell high grade lymphoma." (PMID 30040869, 2018).
bacterial sepsis (1 paper, 2022). "Preclinical studies have shown that bacterial sepsis leads to increased expression of CTLA-4 on CD4+ and CD8+ T cells, and anti-CTLA-4 treatment exhibits dose-dependent reductions in CD4+ and CD8+ T lymphocyte apoptosis and improved survival." (PMID 36518755, 2022).
bovine diseases (1 paper, 2019). "In order to deepen the understanding of the mechanism of the immune response in bovine diseases, we established a bovine recombinant CTLA-4 and monoclonal antibody against bovine CTLA-4 for functional analysis." (PMID 31665022, 2019).
cardiac hypertrophy (1 paper, 2022). "Morphological characterization of the myocardial tissue phenotype in mice after short-term anti-CTLA-4 or anti-PD-1 treatment clearly indicates no cardiac hypertrophy with the exception of Pembrolizumab." (PMID 36158826, 2022).
cervical tumour (1 paper, 2019). "Our data indicate that the cervical tumour cells express markers associated with activation of the immune system (CD95 and MICA/B), as well as markers related to inhibition of the immune system (CD73, CD39, CTLA-4, and CD25)." (PMID 31198791, 2019).
Chagas cardiomyopathy (1 paper, 2022). A disease of the cardiac muscle developed subsequent to the initial protozoan infection by trypanosoma cruzi. "Thus, we suggested that this CTLA-4-mediated suppression mechanism could be used by Treg cells only in IND, but not by CARD patients, since Chagas cardiomyopathy patients demonstrated a higher frequency of Treg CD28+ lymphocytes and not CTLA-4, as shown by IND patients in our previous studies." (PMID 35665256, 2022).
Chediak-Higashi syndrome (1 paper, 2014). ChC)diak-Higashi syndrome (CHS) is a rare severe genetic disorder generally characterized by partial oculocutaneous albinism (OCA), severe immunodeficiency, mild bleeding, neurological dysfunction and lymphoproliferative disorder. "Activated T cells in the lymphoproliferative disease Chediak-Higashi syndrome (CHS) lacking CTLA-4 expression have been proposed to play a role in CHS." (PMID 24515439, 2014).
chronic bronchitis (1 paper, 2013). A type of chronic obstructive pulmonary disease characterized by chronic inflammation in the bronchial tree that results in edema, mucus production, obstruction, and reduced airflow to and from the lung alveoli. "CTLA-4 gene polymorphisms are also associated with chronic bronchitis or COPD." (PMID 24289273, 2013).
Chronic T-cell leukemias (1 paper, 2016). "Chronic T-cell leukemias were found to be negative for CTLA-4 in a few cases." (PMID 26918337, 2016).
chronic tonsillitis (1 paper, 2021). "In this paper, an expression of CTLA-4 at the germinal center of the lymphatic follicles of palatine tonsils was observed in the elder patients with chronic tonsillitis." (PMID 33490647, 2021).
clear cell ovarian carcinoma (1 paper, 2026). "Dual checkpoint blockade with PD-1 and CTLA-4 inhibitors demonstrates enhanced antitumor activity, particularly in clear cell ovarian carcinoma (CCOC), albeit at the expense of increased immune-related toxicity." (PMID 42278449, 2026).
Corneal opacity (1 paper, 2013). A reduction of corneal clarity. "Similar results are seen when measuring the development of corneal opacity with a slight reduction in the kinetics of rejection in recipients of CTLA4-KDEL-expressing DCs." (PMID 23212959, 2013).
cranial nerve palsy (1 paper, 2024). Injury to any of the cranial nerves or their nuclei in the brain resulting in muscle weakness. "Looking at cranial nerves palsy according to ICI class, we observed that most patients with facial nerve involvement were under anti-CTLA-4, 57% (n = 12)." (PMID 39225744, 2024).
cutaneous vasculitis (1 paper, 2021). Inflammation of the blood vessel wall characterized by palpable purpura. "We observed that the mean fluorescence intensity (MFI) of PD-1 and CTLA-4 in the CD4+ T-cell population was notably increased in patients with cutaneous vasculitis compared to the HD." (PMID 34625602, 2021).
cyst (1 paper, 2023). A sac-like closed membranous structure that may be empty or contain fluid or amorphous material. "Notably, kidney cyst number did not significantly change, but cyst size showed a trend toward smaller cysts, in mice that received both anti–PD-1 and anti–CTLA-4, suggesting that combination treatment predominantly impacted cyst expansion and not cyst initiation." (PMID 37345660, 2023).
dementia (1 paper, 2022). Loss of intellectual abilities interfering with an individual's social and occupational functions. "Therefore, we wanted to determine whether also the expression of the T cell co-stimulatory markers CD28, ICOS and CTLA-4 was affected by dementia." (PMID 34427746, 2022).
digestive (1 paper, 2020). "Secondly, environmental factors might also influence relationship between CTLA-4 polymorphisms and digestive system malignancies." (PMID 32178688, 2020).
dry eyes (1 paper, 2021). "Abatacept, a CTLA4-Iginitially developed as a competitive inhibitor of CD28/B7 pathway that acts against CD4 + T-cells, better impacts dry eyes and mouth." (PMID 33917955, 2021).
ductal carcinoma in situ (1 paper, 2018). "Group I, summary of the breast tissue cores with ductal carcinoma in situ showing the CTLA-4 staining reactions, scores, interpretations, and percentages of stained lymphocytes." (PMID 29672601, 2018).
dysgerminoma (1 paper, 2025). A malignant germ cell tumor characterized by the presence of a monotonous primitive germ cell population. "When we compared the normalized counts of these immune checkpoints across the pediatric GCT subtypes, we found that dysgerminoma showed significantly higher expression of IDO1 and CTLA4 than the control group." (PMID 40621458, 2025). "Dysgerminomas exhibited an immune-active profile with elevated levels of T cells, CD8+ T cells, and cytotoxic cells, alongside upregulation of immune checkpoints CTLA4, TIGIT, and IDO1, suggesting potential responsiveness to checkpoint inhibitors." (PMID 40621458, 2025). "TIGIT, IDO1, CTLA4, and PDCD1 were specifically upregulated in dysgerminomas." (PMID 40621458, 2025). "In dysgerminomas, targeting IDO1 and CTLA4 could enhance T cell-mediated anti-tumor responses." (PMID 40621458, 2025).
dysplasia (1 paper, 2015). A usually neoplastic transformation of the cell, associated with altered architectural tissue patterns. "However, CD80 signaling augmentation by means of anti-CTLA4 administration failed to completely eradicate the dysplasia." (PMID 25595911, 2015).
empty sella syndrome (1 paper, 2024). Empty sella syndrome (ESS) is a condition that involves the sella turcica, a bony structure at the base of the brain that protects the pituitary gland. "Secondary empty sella was only seen in patients treated with anti-CTLA-4/PD-1 combination therapy." (PMID 39135626, 2024).
endometrioid tumor (1 paper, 2024). A benign, borderline, or malignant epithelial tumor of the female reproductive system characterized by the presence of glands and/or cysts lined by neoplastic cells that resemble endometrial cells. "In contrast, endometrioid tumors were indicated to have a stronger presence of Tregs (FOXP3 and CTLA-4), and tumor PD-L1 and IDO1 levels on par with HGSC." (PMID 39026018, 2024).